BRCA1 (BRCA1 DNA repair associated)
Diseases named in the same sentence as BRCA1 in open-access papers (continued):
Sharing a sentence is not in itself a finding about the gene and the disease.
breast cancer (continued). "As an example, mutations in the BRCA1 and BRCA2 genes are well known to be associated with increased risk of breast cancer." (PMID 39729424, 2024). "There are 1508 BRCA1 and BRCA2 mutation carriers, 12,265 breast cancers (8755 diagnosed before age 45) at enrolment with age‐matched population‐ and family‐based controls, 2250 incident breast cancers including 1135 in those unaffected at baseline." (PMID 38504141, 2024). "Acquired resistance to PARP inhibitors (PARPi) remains a treatment challenge for BRCA1/2-mutant breast cancer that drastically shortens patient survival." (PMID 38956205, 2024). "Germline pathogenic variants in BRCA1 and BRCA2 genes (gBRCAm) are the most common hereditary breast cancer predisposition." (PMID 39319938, 2024). "On the other hand, BRCA1 and BRCA2 carriers face a 50–59% and 42–51% breast cancer risk, and 34–45% and 13–21% ovarian cancer risk respectively, as well as a two-to threefold risk of endometrial cancer." (PMID 38698439, 2024). "Data are scarce on the role of pathogenic germline variants in BRCA1 and BRCA2 (gBRCAm) in subtype-specific survival in young women who develop breast cancer under the age of 40." (PMID 38398129, 2024). "With this in mind, several initiatives have been established such as “ENIGMA consortium” aiming to determine the clinical significance of sequence variants in BRCA1, BRCA2 and other known or candidate breast cancer susceptibility genes." (PMID 38313678, 2024). "In BRCA1 PV breast cancers, the promotor region of the ERα is highly methylated compared to the sporadic breast cancers." (PMID 39682099, 2024). "Although it has been shown that Resveratrol regulate BRCA1 gene expression in breast cancer cells and that MBD proteins bind to the BRCA1 gene promoter regions, the molecular link or mechanism has yet to be established." (PMID 38711004, 2024). "One explanation for the majority of practises focussed on breast cancer is due to the available prevention options and the fact that testing for hereditary cancer (e.g., BRCA1/2 genes) is available for a number of decades." (PMID 39346592, 2024). "The detection rate of validated breast cancer genes beyond BRCA1/2 and CHEK2 from the current study, and the literature, is low at ~2%." (PMID 38609177, 2024). "We found that in response to estrogen (17β-estradiol, E2) Gata3+/− and Brca1+/− mouse mammary tumor cells expressed higher levels of γH2AX than Gata3+/+;Brca1+/+ tumor cells." (PMID 38627785, 2024). "As a control, we conducted a similar treatment for Brca1+/− (p18−/−;Brca1+/−) mouse mammary tumor cells and also observed a significant increase of γH2AX in Brca1+/− cells relative to that in Gata3+/+;Brca1+/+ cells." (PMID 38627785, 2024). "Another study compared the age at breast cancer diagnosis with DH and SH in the BRCA1 and BRCA2 genes." (PMID 39061189, 2024). "Her medical history included BRCA1-positive breast cancer diagnosed three years prior, accompanied by lung metastases." (PMID 39768480, 2024). "Genetic factors (such as BRCA1 and BRCA2 gene mutations) and hormone levels (especially estrogen) are the main risk factors for breast cancer." (PMID 39767777, 2024). "We determined that 106 of these genes, including breast cancer type 1 (BRCA1), SUZ12 polycomb repressive complex 2 subunit (SUZ12), and FA complementation group M (FANCM), were involved in the cell cycle process." (PMID 38514462, 2024).
breast cancer (continued). "Here, we evaluated the performance of BOADICEA in predicting 5-year breast cancer risks in a prospective cohort of BRCA1/2 PV carriers ascertained through clinical genetic centres." (PMID 38834293, 2024). "This study sought to explore the patterns and outcome of CNS metastases in breast cancer patients with germline PVs in BRCA1/2 genes." (PMID 38365640, 2024). "Since the breast cancer cell marker BRCA1 is overexpressed in the lung of mice receiving DOX treatment, it has been observed that DOX increases the risk of metastasis." (PMID 38796426, 2024). "The RAD51 protein is known to interact with a series of proteins involved in breast cancer regulation including BRCA1/2." (PMID 39282472, 2024). "According to the latest research data, this paper analyzes the cost-effectiveness of Talazoparib and the standard treatment group as BRCA1/2 mutant advanced breast cancer treatment schemes for the first time." (PMID 38886516, 2024). "Third, due to the small number of breast cancer patients carrying BRCA gene variants, this study was unable to analyze the differences in clinical characteristics between patients carrying BRCA1 gene variants and those carrying BRCA2 gene variants." (PMID 38167124, 2024). "Recent comprehensive studies have highlighted that pathogenic variants (PVs) across eight distinct genes, such as ATM, BRCA1, BRCA2, CHEK2, PALB2 (FANCN), RAD51C, and RAD51D, exhibit a substantial correlation with breast cancer risk." (PMID 38397209, 2024). "Germline pathogenic variants (PVs) in ATM, BRCA1, BRCA2, CHEK2, and PALB2 are detected in 5-7% of unselected women with breast cancer in the general population and are associated with a significantly increased risk of breast cancer in unaffected women." (PMID 39624521, 2024). "Breast cancer gene 1 (BRCA1) carriers are prone to lung and lymph node metastasis, while breast cancer gene 2 (BRCA2) carriers tend to have bone metastasis." (PMID 38586673, 2024). "However, seven out of nine (77.8%) of our DH carriers harbored a BRCA1 mutation, and four of them (44.4%) developed bilateral breast cancer, suggesting Chinese DH individuals may have a higher chance of having bilateral breast cancer than other populations (p = 0.0237)." (PMID 39061189, 2024). "In this cohort study of BCT in pathogenic BRCA1/2 variant carriers, we found that women with breast cancer and pathogenic variants in BRCA1/2 treated with BCT have quantifiable above-average risks of ipsilateral and contralateral breast cancer events." (PMID 38916888, 2024). "Among all breast cancer patients, TNBC patients are more likely to have BRCA1/2 germline mutations, with a prevalence rate of approximately 10–20%5–8." (PMID 38689097, 2024). "The first breast cancer gene (BRCA1) was identified in 1994, showing close correlation with breast cancer development when becoming mutated, while the second breast cancer gene (BRCA2) was announced in 1995." (PMID 38672654, 2024). "Recently, even a patient with breast cancer and concurrent PVs in three cancer-related genes (BRCA1, BRCA2, and CHEK2) has been reported." (PMID 38929805, 2024). "In this study, we describe new mouse models, based on Brca1-def and Bard1-def orthotopic allografts, that recapitulate the clinical response and progression phases of PARPi therapy observed in BRCA1/2-mutant breast cancer patients." (PMID 38956205, 2024).
breast cancer (continued). "It is noteworthy that BRCA1 and FANCD2 mutation carriers commonly have KRT14-positive breast tumors and among sporadic breast cancer patients those with KRT14-positive tumors have markedly poorer prognosis than the patients with KRT14-negative tumors." (PMID 38597967, 2024). "Studies of populations in the USA or Europe have shown that BRCA1 and BRCA2 mutations have a 24–35% and 19–29% risk of developing contralateral breast cancer within 10 years of their first breast cancer." (PMID 38254240, 2024). "PARP inhibition has been used as monotherapy in the treatment of BRCA1- or BRCA2-mutant breast cancers." (PMID 39730675, 2024). "Hsa-miR-498 was revealed to downregulate BRCA1, one of the pivotal genes involved in breast cancer progression signifying its role in therapeutics." (PMID 38326829, 2024). "Concerning breast cancer, the 1CM-involved genes are highly overlapped in the alterations derived from the breast cancer network, which uses BRCA1, BRCA2, CHEK2, and ATM as reference genes for the disease." (PMID 39125744, 2024). "In most sporadic breast cancers with intact BRCA1 and BRCA2 genes, the C-terminal domain of the BRCA protein interacts with histone deacetylases to promote the deacetylation of histones as well as other genes." (PMID 39682099, 2024). "Heterozygous mutations in any of three major genes, BRCA1, BRCA2 and PALB2, are associated with high-risk hereditary breast cancer susceptibility frequently seen as familial disease clustering." (PMID 38597967, 2024). "Likelihood‐ratio in favor of pathogenicity was 98898642.82 under assumption of standard BRCA1 breast and ovarian penetrance, and 104240832.84 after excluding breast cancer diagnoses (based on penetrance results)." (PMID 39194334, 2024). "FDA-approved therapies specific to breast cancer include Olaparib, which has demonstrated clinical efficacy for patients with ATM, BRCA1/2, and CHEK2 mutations, as well as alpelisib for patients with PIK3CA mutations." (PMID 38927753, 2024). "The methylation of BRCA1 promoter was first identified in sporadic breast cancer in 1997, and PARPi therapy was subsequently recommended for BRCA1 methylated cancers." (PMID 37588193, 2024). "This inflammatory signalling in breast cancers has been found to be augmented in the presence of BRCA1/2 PVs, as evidenced by the higher rates of lymphocytic infiltration as compared to sporadic breast cancers generally." (PMID 39682099, 2024). "The risk of breast cancer was highest for women with a pathogenic variant in BRCA1 or BRCA2: hazard ratio (HR) of 16.2 (95% CI: 10.9-24.1, P = 2.6e−76) for BRCA1 and HR = 8.5 (CI: 5.8-12.5, P = 1.3e−39) for BRCA2." (PMID 39669587, 2024). "BRCA1/2 gene mutation is one of the most common causes of hereditary breast cancer, which occurs in about 20% of cases with family history, and BRAC1 breast cancer is more likely to form poorly differentiated cancer." (PMID 38886516, 2024). "Germline pathogenic variants in BRCA1 and BRCA2 account for approximately 5% of all breast cancers and up to 30% of hereditary breast cancer." (PMID 38869771, 2024). "Risk factors include mutations in the BRCA1 or BRCA2 genes, which are associated with a tenfold increase in the risk of developing breast cancer." (PMID 39409110, 2024). "Then, we focused on deleterious mutations of BRCA1 and BRCA2, the most crucial genes increasing the risk of ovarian and breast cancer." (PMID 38509102, 2024). "It has been reported that BRCA1 inhibition leads to centrosome amplification and aneuploidy, which promotes breast cancer tumor progression." (PMID 38606093, 2024).
breast cancer (continued). "Specific regions known as the breast cancer cluster regions (BCCRs) within BRCA1 are localized at coordinates c.179–505, c.4328–4945, and c.5261–5563." (PMID 38397209, 2024). "Drug efflux, BRCA1/BRCA2 reverse mutations, epigenetic modification and restoration of PARylation79 were found in breast cancer." (PMID 37588193, 2024). "Our results from all-comers population genetic screening confirmed that rare pLOF variants in BRCA1, BRCA2, PALB2, ATM, and CHEK2 confer significant risk to breast cancer in the overall population." (PMID 39669587, 2024). "Following the first report on mosaic BRCA1 epimutations in white blood cells (WBC) from breast cancer patients in 2008, a number of studies confirmed the same observation among breast and ovarian cancer patients." (PMID 40225940, 2024). "Triple-negative breast cancer is prevalent in BRCA1 mutation carriers, whereas estrogen receptor-positive, HER2-negative luminal breast cancer is more common in BRCA2 mutation carriers." (PMID 39174799, 2024). "Additionally, gene screening is becoming increasingly important in breast cancer diagnosis, particularly for women with a family history of the disease, as it can identify inherited genetic mutations that may elevate the risk of breast cancer, such as mutations in the BRCA1 and BRCA2 genes." (PMID 38534493, 2024). "Ongoing research efforts have highlighted the importance of HRD beyond BRCA1/2 as a potential therapeutic target in breast cancer." (PMID 38822929, 2024). "The annualized cumulative incidence rate of contralateral breast cancer among unilateral breast cancer cases with germline PVs in BRCA1 and BRCA2 genes is 2.3% and 1.7% per year, respectively." (PMID 38893140, 2024). "In ovarian and breast cancer, promoter methylation of BRCA1 or RAD51C is a promising biomarker for PARP inhibitor response, as high levels lead to homologous recombination deficiency (HRD)." (PMID 39055334, 2024). "BRCA1 and BRCA2 are well-characterized breast cancer susceptibility genes and it is well established that mutations in these genes impair the homologous recombination–mediated DNA repair pathway, which is required to maintain genomic integrity." (PMID 38059556, 2024). "There are several polymorphisms of BRCA1 and BRCA2 associated with increased risk of sex-specific cancers such as breast cancer, ovarian cancer, and endometrial cancer in women and prostate cancer in men." (PMID 38952711, 2024). "In breast cancer cells, depletion of BRCA1 or PALB2 diminishes the anti-proliferative effect exerted by ATRA." (PMID 38360674, 2024). "Our results extend those from BCAC and the Consortium of Investigators of Modifiers of BRCA1/2 (CIMBA) investigations of first primary breast cancers." (PMID 39786405, 2024). "For BRCA1, peak breast cancer incidence occurs between 41 and 50 years, whereas for BRCA2 and PALB2, peak incidence occurs between 51 and 60 years of age." (PMID 38248108, 2024). "The graph shows interactions between miR-16, miR-21, miR-195, and miR-210 with different target genes of breast cancer pathways at the same level, including interactions with highly penetrant genes such as BRCA1 and BRCA2." (PMID 38813102, 2024). "Although a number of high-risk breast cancer genes have been identified, including BRCA1 and BRCA2, the risk profile of many high-risk families cannot be explained using known breast cancer genes." (PMID 38397208, 2024). "Resistance to PARP inhibitors (PARPi) remains a major treatment challenge in BRCA1/2-mutant breast cancer." (PMID 38956205, 2024).
breast cancer (continued). "To this end, we screened a total of 1735 females for WBC BRCA1 promoter methylation, 908 of whom had been diagnosed with breast cancer, and whose median age was 49 years, and 827 healthy female controls ranging in age from 15 to 50 years." (PMID 38542081, 2024). "In summary, our data indicate that PARP inhibition radiosensitizes both BRCA1-mutant and BRCA1-recovered breast cancer cells to photons and protons." (PMID 39730675, 2024). "Especially, the inherited risk for ovarian cancer associated with pathogenic variants in BRCA1 and BRCA2 is of clinical relevance and has a direct impact on the survival of women treated for BRCA1/2-associated breast cancers." (PMID 38491334, 2024). "BRCA mutations (BRCA1 or BRCA2), which affect approximately 3–5% of breast cancer patients, are clinically significant in treatment decisions." (PMID 39484212, 2024). "UTP6 was enriched in the process of snoRNA binding, while snoRNA activated PARP-1 ADPRylates DDX21 in BRCA1/2-wild-type breast cancer cells to promote enhanced ribosome biogenesis and cell proliferation." (PMID 39095659, 2024). "As in other Spanish population studies, the number of PVs was slightly higher in the BRCA2 gene than in the BRCA1 gene, and males with breast cancer in our study only had PVs in BRCA2." (PMID 39438962, 2024). "Our study investigated how BZA affects certain key proteins associated with Estrogen Receptor Alpha (ERα) and tumor suppressor gene BRCA1 in breast cancer cells." (PMID 38398090, 2024). "BRCA1 and BRCA2’s PVs were associated with breast cancer, ovarian/fallopian cancer, pancreas cancer, prostate cancer, and melanoma, while breast, prostate, thyroid, kidney, colon and stomach cancers were related to PVs in CHEK2." (PMID 38929805, 2024). "For the gene BRCA1, it is considered not only playing a vital role on the breast cancer pathway, but also involving in the ribosome biogenesis." (PMID 38654350, 2024). "Comparing to the higher breast cancer RRs at younger age for both BRCA1 and BRCA2 carriers, the RRs for ovarian cancer increased with age for both mutations." (PMID 38333895, 2024). "The emergence of drug resistance is a major clinical challenge that limits the efficacy and durability of PARPi therapies for BRCA1/2-mutant breast cancer patients." (PMID 38956205, 2024). "In this study, we generated new in-vivo treatment models of Brca1- and Bard1-mutant breast cancer that recapitulate the striking response to PARPi, acquired resistance, and recurrence that is observed in patients with breast cancer." (PMID 38956205, 2024). "According to the results of this trial, Talazoparib is more effective than standard treatment for patients with BRCA1/2 mutant advanced breast cancer." (PMID 38886516, 2024). "Proteins related to the cell cycle and cancer, e.g., breast cancer (estrogen receptor, BRCA1) and adenomatous polyposis coli (APC), a known oncogenic driver gene in CRC, were also identified." (PMID 38177114, 2024). "In one retrospective cohort of 184 BRCA1/2 carriers with epithelial ovarian cancer, only 16 (8%) developed breast cancer at a median of 7 years’ follow-up." (PMID 38248108, 2024). "In human breast cancer, there is evidence of a correlation between nuclear BRCA1 and WWOX expression." (PMID 38499540, 2024). "This is in alignment with a pervious study on BRCA1/2-negative women with invasive breast cancer and a family history of breast cancer." (PMID 38351438, 2024). "Since breast cancers with defective BRCA1 and HR pathway are sensitive to DNA damage-inducing anticancer drugs such as PARPi, our study provides a novel target for the treatment of breast cancer, as well as the development of anticancer drugs." (PMID 38734703, 2024).